CD109 (CD109 molecule)
Diseases named in the same sentence as CD109 in open-access papers (continued):
Sharing a sentence is not in itself a finding about the gene and the disease.
tumor (continued). "While CD109 has the ability to inhibit TGF-β-induced EMT and to enhance migration of cancer cells, it may promote tumor initiation and metastasis by enhancing the EGF or the JAK-STAT3 pathway." (PMID 31695056, 2019). "We hypothesized that when the tumor-promoter function of TGF-β predominates, CD109 can repress TGF-β induced EMT, leading to a decrease in motility and invasion." (PMID 31695056, 2019). "Our results demonstrating that knockdown of CD109 in hBM-MSCs abrogates the inhibitory effects of hBM-MSC-CM on EMT, migration, invasion and spheroid formation in SCC cells, indicate that CD109 released from hBM-MSCs is essential for these anti-tumor effects." (PMID 29221155, 2017). "To investigate whether the anti-tumor activity of hBM-MSC-CM could be dependent on the released CD109 in the conditioned medium, we knocked down CD109 in hBM-MSCs using small interfering RNA (siRNA)." (PMID 29221155, 2017). "Tumor-secreted CD109 was detected in sera of HEK293-FLAG-hCD109 xenografted mice; quantitative assessment by CD109 ELISA showed a logarithmic increase in parallel to that of xenografted tumor volume." (PMID 24400073, 2014). "The CD109 ELISA used in this study detects only human CD109, not mouse CD109, and clearly detected an exponential increase in tumor-produced human CD109 concentration." (PMID 24400073, 2014). "However, the implications of CD109-mediated TGF-β inhibition on tumor progression in MFS have not yet been clearly investigated." (PMID 41562047, 2025). "CD109’s known ability to regulate TGF-β signaling may influence the dynamic balance between TGF-β’s tumor-suppressive and pro-tumorigenic effects, particularly in the inflammatory tumor microenvironment." (PMID 39990858, 2024). "Furthermore, CD109 induces EGFR-mediated STAT3 phosphorylation, which supports SCC cell migration, proliferation, and the cancer stem cell phenotype in vitro, suggesting its role in enhancing tumor aggressiveness and inflammation." (PMID 39990858, 2024). "CD109 influences key inflammatory pathways, including TGF-β/NF-κB, EGF/STAT3, and various inflammatory cytokines like IL-6 and IL-8, impacting inflammatory processes such as immune cell recruitment, macrophage polarization, immune microenvironment, EMT, and tumor progression." (PMID 39990858, 2024). "The enrichment/activation of connective tissue development function and exclusive expression of CD87, CD91, CD109, and CD280 by NCI-H23 cells in 3D culture are in direct agreement with the ability of 3D cultured cells to phenotypically mimic and begin to recapitulate the tumor microenvironment." (PMID 34611477, 2021). "Still, to date CD109 have not been reported in exosomes derived from SCC or other tumor cells." (PMID 29625613, 2018). "Altogether, these results strongly suggest that CD109 released into hBM-MSC-CM is at least partially responsible for the suppression of cancer cell migration and invasiveness, since the knockdown of CD109 in hBM-MSC abrogates the anti-tumor activities of hBM-MSC-CM." (PMID 29221155, 2017). "In the study, we found that CD109-specific aptamer S3, but not unselected ssDNA library, could recognize the tumor spheres." (PMID 27419372, 2016). "Moreover, at cut-off value ≥5% tumour cells with positive immunostaining, the expression CD44 was found to be accompanied by the co-expression with individual members of the HER family as well as EGFRvIII (83%), CD109 (16%), HER2/EGFRvIII (65%), or HER2/HER4/EGFRvIII (55%)." (PMID 40227788, 2025). "Beyond its diagnostic and prognostic relevance, the inhibitory effect of CD109 on TGF-β signaling could mitigate tumor-promoting immunosuppression, restrain M2-like macrophage polarization, and restore T cell activity, thereby potentially enhancing anti-tumor immunity." (PMID 41562047, 2025).
tumor (continued). "Furthermore, CD109 is highly expressed in well-differentiated SCCs rather than in moderately or poorly differentiated SCCs, thus the expression level of CD109 is inversely correlated with tumor grade." (PMID 29625613, 2018). "However, we cannot rule out the possibility that CD109 may act as a tumor promoter under conditions - differing from those of the current experimental setting." (PMID 29221155, 2017). "However, the expression of CD109 in tumor vessels and its clinical significance were not mentioned." (PMID 27121053, 2016). "Additionally, CD109’s interaction with EGFR could amplify pro-inflammatory cytokine production, such as IL-6 and IL-8, by activating downstream pathways like Akt/mTOR and NF-κB, thereby enhancing tumor growth, immune suppression, and potentially contributing to chemoresistance." (PMID 39990858, 2024). "However, CD109 could not discriminate tumor-derived circulating EC from normal circulating EC." (PMID 27121053, 2016).
cancer (50 papers, 2012 to 2026). A tumor composed of atypical neoplastic, often pleomorphic cells that invade other tissues. "CD109 is implicated in promoting cancer cell proliferation and metastasis through the JAK/STAT signaling pathway." (PMID 39099698, 2024). "Recently, a meta-analysis has proved the association between the high level of CD109 expression and poor overall survival in cancer patients, suggesting the use of CD109 as a prognostic." (PMID 37468977, 2023). "An association between CD109 expression and OS in other types of cancer has been described." (PMID 36134447, 2022). "ALDH1 participates in drug detoxification and is well recognized as a surface marker for cancer stem cells, implying that CD109 expression might associate with stem-like feature." (PMID 33375719, 2020). "Furthermore, it has been pointed out that CD109 was associated with the tumorigenicity and carcinogenesis of several human carcinomas." (PMID 32507856, 2020). "We believe that our two novel anti-CD109 mAbs, which are directed against two distinct epitopes on the extracellular domain of CD109, are ideal tools for conducting detailed studies of the biological significance and diagnostic, prognostic and predictive values of CD109 in human cancers." (PMID 29731998, 2018). "Here we show that CD109 plays a pivotal role as an essential regulator of IL6Rα expression and IL-6-driven oncogenic processes, enhancing cancer cell stemness and antioxidant capabilities in SCC cells." (PMID 40317079, 2025). "Our findings establish CD109 as an essential regulator of IL-6-mediated oncogenic activity promoting cancer cell stemness and antioxidant state in SCC cells, providing mechanistic insights into IL-6-mediated cell survival and resistance to therapy in SCC." (PMID 40317079, 2025). "Recent reports by us and others suggest that CD109 promotes cancer progression by potentiating epidermal growth factor receptor (EGFR) signaling in SCC cells." (PMID 40317079, 2025). "CD109’s multifaceted role in inflammation spans various tissue types, including the skin, lung, bone and bone-related tissues, and various types of cancers." (PMID 39990858, 2024). "CD109, an inositol-anchored glycoprotein expressed in numerous cancers, emerges as one of the regulatory factors governing bone homeostasis." (PMID 39099698, 2024). "CD109 exerts its effects by modulating processes such as cytokine secretion, immune cell recruitment, macrophage polarization, T helper cell function and cancer cell phenotype and function." (PMID 39990858, 2024). "In the current study, we show that a protein called CD109 plays an important role in the progression of this type of cancer." (PMID 35954339, 2022). "The expression of CD109 is dysregulated in many cancers including SCC, and high levels of CD109 are frequently detected in premalignant lesions of the oral cavity, which are associated with a significantly higher risk of progressing toward an overt SCC." (PMID 35954339, 2022). "As STAT3 is a central driver of cell survival and inhibition of apoptosis in cancer, we determined the impact of CD109 silencing on cell viability." (PMID 33986188, 2021). "Although few reports have described the use of serum samples, recently, many research groups have focused on CD109 and have reported the upregulation of its immunohistochemical expression in multiple types of malignant tumors." (PMID 33565282, 2021). "CD109 was involved in the tumorigenesis and progression of various cancers via TGF-β1 signalling and STAT3 activation." (PMID 32507856, 2020). "In conclusion, our findings imply that CD109 mediates tumorigenicity and cancer aggressiveness in cervical squamous carcinoma cells." (PMID 32507856, 2020). "In the current study, we further identified that CD109 expression was significantly associated with EMT and stem-like signatures, and activation of YAP participated in the CD109-elicited EMT and cancer stemness traits." (PMID 33375719, 2020).
cancer (continued). "A precise definition of the molecular pathways regulated by CD109 and the consequences of their dysregulation in cancer progression and metastasis remain to be determined." (PMID 31695056, 2019). "Recently, the glycoprotein CD109 was shown to associate with many cancers including GBM; and CD109 and YAP/TAZ are known to regulate some overlapping biological pathways in cancer." (PMID 31231648, 2019). "It is therefore possible that the consequences of loosing CD109 in cancer progression and metastasis are more complex." (PMID 31695056, 2019). "In SCC, an inverse correlation between CD109 expression and the grade of the cancer has been reported, with CD109-positive tumors being well differentiated and of a lower grade, whereas CD109-negative tumors being poorly differentiated and of a higher-grade." (PMID 29221155, 2017). "Our findings indicate that hBM-MSCs inhibit the malignant traits of SSC cells by a paracrine effect via released factors and that the anti-cancer effect of hBM-MSC is at least in part due to CD109 released from hBM-MSCs." (PMID 29221155, 2017). "Altogether, our results suggest that hBM-MSC-CM possesses potent anti-cancer activity and that it involves CD109-mediated inhibition of EMT and stemness." (PMID 29221155, 2017). "These discrepant results reported on the role of BM-MSCs on cancer cell behaviour can be partially explained by the role of CD109 as a strong TGF-β antagonist, inhibiting the dual effects of TGF-β on cancer cells." (PMID 29221155, 2017). "Following an approach recently validated in our laboratory, we investigated the expression of CD109 on CECs from the peripheral blood of healthy subject and cancer patients." (PMID 25506915, 2014). "The role of CD109 expression in cancer vessel-specific endothelial cells deserves to be further investigated by gene expression studies." (PMID 25506915, 2014). "In order to gain a more comprehensive understanding of CEC phenotype, we investigated the expression of CD109 on cultured endothelial cells and on CECs from the peripheral blood of healthy subject and cancer patients." (PMID 25506915, 2014). "Endothelial colonies from all healthy subjects and from 10 cancer patients were also evaluated for CD109 expression." (PMID 25506915, 2014). "CD109 was expressed on 1/9 endothelial cultures from healthy subject (11%) and on 5/10 (50%) endothelial cultures from cancer patients." (PMID 25506915, 2014). "Although CD109 is expressed in a variety of cell types and its expression is altered in many types of cancer, the function of this protein is poorly understood." (PMID 22694813, 2012). "The expression of both CD44 and CD109, which act as putative cancer stem cell biomarkers, facilitate cancer progression and resistance to treatment, making them promising targets for therapeutic strategies in various cancers." (PMID 40227788, 2025). "CD44 and CD109 are both cell surface glycoproteins that play significant roles in cancer biology." (PMID 40227788, 2025). "Given the known role of the IL-6/STAT3 pathway in enhancing cancer cell stemness, it was of interest to explore whether CD109-mediated IL6Rα/STAT3 pathway activation leads to increased stemness." (PMID 40317079, 2025). "While the process of EMT has been implicated in hematopoietic malignancies, whether CD109-medited regulation of EMT and inflammation plays a role in the progression of the malignant progression of these cancers remains to be determined." (PMID 39990858, 2024). "A meta‐analysis study illustrated that the expression of the CD109 gene could be a beneficial biomarker of cancer in general." (PMID 38018319, 2024). "Future research could focus on elucidating the precise mechanisms by which CD109 regulates the inflammatory pathways to maintain tissue homeostasis in health and promote oncogenic progression in cancer." (PMID 39990858, 2024).
cancer (continued). "Furthermore, furin induces the processing of CD109 into small proteins which form an intricate complex with type 1 TGF‐β receptor for the direction of TGF‐β signaling in cancer cells." (PMID 38018319, 2024). "Moreover, recent studies have revealed that CD109 is overexpressed in multiple human cancers, including squamous cell carcinoma of the lung, vulva and uterine cervix, adenosquamous carcinoma of the gallbladder, and ductal adenocarcinoma of the pancreas." (PMID 37468977, 2023). "Their work showed that CD109 could be used as a potential biomarker of NPC for early cancer diagnosis and targeted therapy." (PMID 33796540, 2021). "Therefore, aptamer S3 was used to treat not only NPC, but also other cancers with abnormal CD109 expression." (PMID 33796540, 2021). "It was also shown that meprin β can promote transendothelial cell migration by ectodomain shedding of CD99, and hence might play a role in cancer metastasis as proposed for CD109 as well." (PMID 33738281, 2021). "Thus, the clinical significance of the serum CD109 level under a cancer‐bearing status was assessed according to the ratio of the preoperative value to the postoperative value in each case." (PMID 33565282, 2021). "High levels of CD109 have been reported in multiple cancers, including GBM." (PMID 32457905, 2020). "Despite several studies having reported CD109 upregulation in a variety of malignant tumors, its molecular function and detailed regulatory mechanism are still largely unknown." (PMID 33375719, 2020). "CD109 expression has been shown to be dysregulated in many cancers, suggesting that CD109 may play a role in cancer progression." (PMID 29221155, 2017). "Altogether, these results suggest that CD109 inhibits cancer cell migration and invasion." (PMID 29221155, 2017). "Interestingly, CD109 shows a similar expression pattern to cancer stem cell marker CD44, and its overexpression was associated with better cancer-specific survival." (PMID 29207682, 2017). "Moreover, the use of aptamer S3 is not limited to NPC alone as it can be used for all other cancers that have aberrant expression of CD109." (PMID 27419372, 2016). "CD109 overexpression has also been observed in many human cancers." (PMID 26597595, 2016). "Moreover, CD109 mRNA transcript has been studied in various cancers and is found to be highly expressed in squamous cell carcinomas and melanomas." (PMID 23509816, 2013). "In some human cancers, CD109 actually impairs TGF-β/Smad signaling." (PMID 24376795, 2013). "According to the circRNA target profiling and pathway enrichment analysis, the high‐confidence DECs could influence the expression of cancer stem cell‐associated core signature genes such as ALDH1A3, SOX9, CD109, LIF and BMPR1 via negative regulation of miRNAs." (PMID 35579852, 2022). "Recent studies have shown that CD109 is differentially expressed in a variety of human tumors, leading to the suggestion that CD109 may represent a novel biomarker for certain cancers." (PMID 22694813, 2012). "The interactome gene CD109 has shown oncogenic potential in some subtypes of TGCT, as well as other types of cancer." (PMID 35774118, 2022). "We next evaluated CD44 expression by flow cytometry in both CD109 KO and control A431 cells, as CD44 is a cancer stem cell (CSC) marker that is involved in the regulation of CSC survival, self-renewal, and metastatic colonization." (PMID 35954339, 2022). "These include POLK, NIFK, SRGN, CAMP, CD109, and PLAC1 that are upregulated in several cancers resulting in metastasis and poor prognosis." (PMID 33110154, 2020). "In summary, we demonstrate that expression of CD109 regulates YAP signaling, thereby promoting the EMT, stem cell gene expressions, and cancer stemness properties." (PMID 33375719, 2020). "Conversely, the synthesis and expression of CD109, a TGFβ co-receptor used to facilitate the diagnosis of high-grade MFS diagnosis, was maintained constant until high cancer cell line passages." (PMID 30366467, 2018).